C5AR1 (complement C5a receptor 1)
Diseases named in the same sentence as C5AR1 in open-access papers (continued):
Sharing a sentence is not in itself a finding about the gene and the disease.
Sepsis (continued). "In fact, C5aR1 has been proposed as a therapeutic target to treat other inflammatory conditions, including inflammatory bowel disease, neurodegenerative diseases, ischemia-reperfusion injury, and general sepsis." (PMID 29362231, 2018). "Our data from ex vivo infections of human whole blood as well from in vivo mouse infections suggest the enticing possibility that C5aR1 might be a therapeutic target for adjunctive treatment of N. meningitidis sepsis." (PMID 29362231, 2018). "There is a C5aR2-dependent upregulation of HMGB1 in sepsis both in vivo and in vitro, while in the context of cerebral malaria induced by Plasmodium falciparum it is C5aR1, but not C5aR2, that causes the elevated plasma HMGB1." (PMID 28706957, 2017). "Additionally, transcriptome screening revealed that the coagulation cascade and complement pathways, along with the receptor C5aR1, might be significant mediators of sepsis-induced WMI." (PMID 41584453, 2025). "Collectively, these findings indicate that glycine represents a promising therapeutic strategy for the prevention and treatment of sepsis-associated WMI, and that targeting the C5aR1-mediated complement pathway may offer a novel approach to mitigate neuroinflammation and white matter damage." (PMID 41584453, 2025). "Interestingly, silenced-C5ar1 could improve those damages suggesting high expression of C5ar1 play a crucial role in the damages of tissue in sepsis." (PMID 38165570, 2024). "In addition, MV shedding with C5aR1 negatively correlated with survival in sepsis patients." (PMID 29696020, 2018). "In murine models of LPS-induced sepsis and OVA-sensitized allergic asthma, pulmonary expression levels of the complement anaphylatoxin receptors C3aR, C5aR1, and C5aR2 were markedly elevated." (PMID 40963601, 2025). "In the GSE72829 control and sepsis groups, C5AR1 (complement C5a receptor 1) and CSF3R (colony-stimulating factor 3 receptor) had degree 50 and 46, respectively." (PMID 33667236, 2021). "In contrast, C5aR1 is upregulated during burn injury and after cecal ligature and puncture-induced (CLP) sepsis, mediating complement-induced cardio-depressive effects." (PMID 32117238, 2020). "Of note, the reduction of C5aR1 and C5aR2 on neutrophils has been correlated with the occurrence of infectious complications in ICU patients and sepsis-induced MODS." (PMID 30949180, 2019). "This study used WT and C5aR1 knockout (C5aR1-/-) mice to induce CLP-sepsis and stained apoptotic cells in the spleen by TUNEL, whereby WT CLP-sepsis mice had up to 5 times higher apoptotic cells per view field." (PMID 30319602, 2018). "An initial study showed that PMX53, an antagonist of C5aR1 in normal C57BL6/J (wild type, WT) mice reduced heart rate (HR) and appeared to have a protective effect on the heart following induced sepsis." (PMID 26727203, 2016). "This study shown that silenced-C5ar1 inhibited the degree of NET and TLR2 suggesting silenced-C5ar1 may improve the sepsis via the Toll-like receptor signaling pathway." (PMID 38165570, 2024). "Following sepsis, blockade or absence of either C5aR1 or C5aR2 significantly improved survival in animals." (PMID 33450984, 2021). "The neutralization of C5a with antibodies or the absence of C5aR1 prevents the appearance of extracellular histones, cell death and organ failure in sepsis." (PMID 33981650, 2021). "Absence of either C5aR1 or C5aR2 attenuates cardiac dysfunction and improves survival of mice during sepsis." (PMID 32117238, 2020). "Our data clearly demonstrate that in vivo N. meningitidis sepsis immunopathology is ameliorated when C5ar1 is absent in mice or when C5aR1 is blocked." (PMID 29362231, 2018). "Summing up, this study suggested that inhibiting the C5ar1 level can inhibit over-expression ENTs to balance the inflammatory levels in CLP rats and improve the tissue damage in sepsis, providing a basis and new direction for the study of treatment on sepsis patients." (PMID 38165570, 2024).
Sepsis (continued). "In our human setting, we found no expression differences of C5aR1 in neutrophils of preterm infants born from an inflammatory context (amniotic infection syndrome with or without early-onset sepsis) as compared to infants without evidence for inflammation at birth." (PMID 37373467, 2023). "This suggests that a better understanding of the attributes of C5AR1 and its interactions with C5a and the TLR4 pathways could prove useful particularly for maximizing dairy cow resilience against extreme disease outcomes such as sepsis." (PMID 33195534, 2020). "Absence of either C5aR1 or C5aR2 was protective for heart function during sepsis." (PMID 32410859, 2020). "Inhibition or reduction of neutrophil MV shedding by targeting C5aR1 may represent a promising approach in order to protect PMN functionality and restore the MV balance during systemic inflammatory conditions such as PT and sepsis." (PMID 32983087, 2020). "Recently, it was shown that C5aR1 knockout (C5aR1−/−) mice did not have lymphopenia following the induction of sepsis by cecal ligation and puncture (CLP), suggesting that C5a played an important role in regulation of adaptive immunity during the acute bacterial infection." (PMID 27624143, 2016). "In sepsis, C5aR2, not C5aR1, was responsible for the release of HMGB1, which was supported by an observation made by Croker and colleagues that high mobility group bow-1 (HMGB1) production from macrophages was independent on C5aR1-C5aR2 heteromer." (PMID 28706957, 2017).
COVID-19 (54 papers, 2020 to 2025). A disease caused by infection with severe acute respiratory syndrome coronavirus 2. "This C5a–C5aR1–glycosphingolipid pathway- induced pro-inflammatory environment causes the tissue damage in COVID-19 and GD." (PMID 36430817, 2022). "C5aR1 blockade also attenuated platelet-mediated COVID-19-associated thrombogenicity in a process dependent on the formation of neutrophil extracellular traps (NETs)." (PMID 34868021, 2021). "Complement activation, and especially the C5a/C5aR1 axis was also implicated in COVID-19 lung pathology." (PMID 33272291, 2020). "Similarly, C5aR1 has been implicated in viral pathologies, including COVID-19 and influenza-induced lung injury, with positive efficacy using anti-C5aR1 therapies." (PMID 38067135, 2023). "Different studies have highlighted complement activation (e.g. the C5aR1 axis), platelet activation, immune-mediated thrombotic mechanisms, endothelial dysfunction, antiphospholipid antibody, and renin-angiotensin system dysregulation as important actors of COVID-19-associated coagulopathy." (PMID 34422854, 2021). "An increase in soluble C5a levels has been described in serum and that of C5aR1 expression in blood and pulmonary myeloid cells in severe cases, suggesting a role for the C5a–C5aR1 axis in the pathophysiology of ARDS in COVID-19 patients." (PMID 39337843, 2024). "In order to validate the single-cell transcriptome data, lung tissue from post-mortem COVID-19 patients was used for C5aR1 immunostaining and costaining for neutrophil (neutrophil elastase; NE) and macrophage/monocyte (Iba-1) cellular markers." (PMID 37104043, 2023). "Our data further reinforce the possibility of the effective use of inhibitors of C5a/C5aR1 signaling for the treatment of COVID-19." (PMID 37104043, 2023). "C5a/C5aR1 signaling increased locally in the lung, especially in neutrophils of critically ill patients with COVID-19 compared with patients with influenza infection, as well as in the lung tissue of K18-hACE2 Tg mice (Tg mice) infected with SARS-CoV-2." (PMID 37104043, 2023). "Herein, we found that C5a/C5aR1 signaling was increased in patients and in a preclinical mice model of COVID-19." (PMID 37104043, 2023). "The hub protein ITGAM is an essential molecular receptor that plays a vital role in many complements mediated pathways that aggravate the COVID-19 symptoms, such as the C5a-C5aR1 axis in the pathophysiology of acute respiratory distress syndrome." (PMID 37877121, 2023). "Initially, we showed that C5aR1 signaling is selectively enhanced in the lungs of patients with COVID-19 compared with patients with the influenza virus, especially in neutrophils." (PMID 37104043, 2023). "Although our data indicate the importance of C5aR1 signaling in neutrophils, which trigger NETs, that, in turn, contribute to the pathophysiology of COVID-19, it is noteworthy that in TgcKO mice, C5aR1 signaling is also interrupted in macrophages/monocytes." (PMID 37104043, 2023). "Of note, this single-cell transcriptome data set also revealed some degree of expression of C5AR1 in epithelial cells of the BAL fluid of COVID-19 patients." (PMID 37104043, 2023). "For instance, C5aR1 signaling in endothelial cells was found to be a prothrombogenic effector in COVID-19 patients." (PMID 37104043, 2023). "A preliminary cohort study with anti-C5aR1 antibody Avdoralimab in COVID-19 patients with severe pneumonia also showed inhibition of thrombosis and prevention of organ damage." (PMID 36585712, 2022). "Supporting the importance of the C5a/C5aR1 axis is that COVID-19 patients generate C5a as detected in pulmonary lavage in proportion to the severity of the disease and high expression of C5aR1 was found in blood and on pulmonary myeloid cells." (PMID 35350780, 2022). "Lastly, our group recently documented that exposing sera from severe COVID-19 patients to endothelial cells induced platelet aggregation via the engagement of C5a/C5aR1 axis." (PMID 35320941, 2022).
COVID-19 (continued). "We also detected lower levels of the complement 5 receptor 1 (C5AR1/CD88) in patients with COVID-19." (PMID 34403366, 2021). "During the recent outbreak of SARS-CoV-2, the potential protective role of C5aR1 blockage in COVID-19-induced cytokine release and endothelial injury is being discussed." (PMID 33362783, 2020). "Additionally, COVID-19 patients with critical conditions exhibited extensive activation of the C5a-C5aR1 pathway." (PMID 39998235, 2025). "C3, C4 and C5 knockout mice together with Crry, DAF, C3aR and/or C5aR1 and C5aR2 knockout can be used for defining the role of complement in general and C3a-C3aR and C5a-C5aR signaling in the pathogenesis of severe COVID-19 and long COVID-19." (PMID 38368584, 2024). "Finally, we found that the C5aR1 signaling mediated COVID-19 immunopathology through enhancement of neutrophil extracellular traps (NETs) formation." (PMID 37104043, 2023). "C5a/C5aR1 signaling on myeloid cells has a detrimental role in a murine model of COVID-19." (PMID 37104043, 2023). "Indeed, no significant alteration in myeloid cell infiltration in the lungs of COVID-19 mice was observed either with genetic or pharmacological inhibition of C5aR1 signaling." (PMID 37104043, 2023). "The increase in C5aR1 signaling in the lungs of patients and mice with COVID-19 led us to explore whether inhibition of this pathway would have a protective effect." (PMID 37104043, 2023). "Higher expression of MAS-1 (MAS-1high) likely tracked IFhigh, as this signature comprised IF-related genes (e.g., C5AR1, MYD88) and higher baseline expression of MAS-1 associated with higherall-cause mortality hazards during acute COVID-19 as well as in the FHS." (PMID 37311745, 2023). "Thus, further studies will be necessary to address the role of C5a/C5aR1 signaling in cells other than myeloid cells in the pathophysiology of COVID-19." (PMID 37104043, 2023). "A pharmacological C5aR1 antagonist ameliorates COVID-19 in the mouse model." (PMID 37104043, 2023). "These preclinical results indicate that pharmacological inhibition of C5aR1 could be a novel approach to ameliorate COVID-19." (PMID 37104043, 2023). "Furthermore, we show that genetic and pharmacological blockage of C5aR1 signaling in myeloid cells (especially neutrophils) ameliorated COVID-19 lung immunopathology." (PMID 37104043, 2023). "In addition, our human data were validated in a well-accepted preclinical model of COVID-19, in which we also observed an increase in C5aR1 signaling activation in myeloid cells (especially neutrophils) in the lung after SARS-CoV-2 infection." (PMID 37104043, 2023). "C5a/C5aR1 signaling enhances NETs formation to aggravate COVID-19." (PMID 37104043, 2023). "Recently, evidence of complement activation in COVID-19, including elevated serum concentrations of C5a and C5b-9, increased leukocyte CD11b expression (which can result from C5aR1 activation), and post-mortem immunochemistry, has been linked to disease severity." (PMID 37376569, 2023). "Furthermore, the effect of anti-C5aR1 activity in COVID-19 patients with severe pneumonia is currently being assessed in a Phase 2 study with avdoralimab." (PMID 33362783, 2020). "The hypothesis that the blockage of C5aR1 signaling would be beneficial to COVID-19 may open another important question related to secondary infections that are extremely common in patients with COVID-19 and are a critical threat in the current treatments targeting the immune response." (PMID 37104043, 2023). "Therefore, targeting complement at the level of the C5a–C5aR1 axis could control SARS-CoV-2-induced tissue inflammation in COVID-19 in addition to GD patients with COVID-19." (PMID 36430817, 2022). "There is also mounting evidence of a spectrum of pulmonary vasculitis in COVID-19: neutrophilic capillaritis, lymphocytic endotheliitis, lymphocyte-plasma cellular arterial vasculitis, obliterating endarteritis involving C5aR1+ macrophages [7 and MRP8+ mononuclear cell vasculitis." (PMID 33553478, 2021).
COVID-19 (continued). "In addition, C5a-C5aR1 could activate neutrophils and mononuclear cells to secret inflammatory factors, which form the hyperinflammatory response, whereas anti-C5aR1 monoclonal antibodies could suppress acute lung injury in patients with severe COVID-19." (PMID 36960050, 2023). "In order to investigate the role of C5a/C5aR1 signaling in the pathophysiology of COVID-19, initially we assessed bronchoalveolar lavage (BAL) fluid from critically ill patients with COVID-19 requiring invasive mechanical ventilation." (PMID 37104043, 2023). "Particularly, many inflammation genes, such as C5AR1, CD55, CSF3R, CXCL8, FPR1, KLF6, and NFKB1A, were significantly upregulated in Neu and Mono cells of the bone marrow of COVID-19 patients." (PMID 37087411, 2023). "Considering that complement component 5a (C5a), through its cellular receptor C5aR1, has potent proinflammatory actions and plays immunopathological roles in inflammatory diseases, we investigated whether the C5a/C5aR1 pathway could be involved in COVID-19 pathophysiology." (PMID 37104043, 2023). "Since C5a/C5aR1 signaling seems to be involved in the immunopathology of COVID-19, we sought to test the efficacy of DF2593A, an orally acting and selective C5aR1 allosteric antagonist, on SARS-CoV-2–infected Tg mice to explore this candidate for the treatment of COVID-19." (PMID 37104043, 2023). "Thus, in an attempt to gain information about the possible role of C5a in the pathophysiology of COVID-19, we sought to identify the possible cell subtype in the BAL fluid of patients with COVID-19 expressing C5AR1, its main proinflammatory receptor." (PMID 37104043, 2023). "Regarding the mechanisms by which C5aR1 signaling is involved in the lung immunopathology during COVID-19, we ruled out the possibility that this pathway would be crucial in the recruitment of myeloid cells into the SARS-CoV-2-infected lungs." (PMID 37104043, 2023). "Nevertheless, no study performed an in-depth investigation of the outcome of the lack of or blockade of C5aR1 signaling on COVID-19 or the mechanisms behind its role." (PMID 37104043, 2023). "Since C5a/C5aR1 signaling in myeloid cells is involved in the lung immunopathology of COVID-19 but not in the infiltration of these cells into the lung, we investigated its possible role in the local activation of these cells, focusing mainly on neutrophils." (PMID 37104043, 2023). "Similar to what we observed in the lung tissue of COVID-19 patients, immunofluorescence analyses of the lung tissue of SARS-CoV-2-infected Tgfl/fl mice revealed that C5aR1 was mainly expressed in cells positive for NE (neutrophils, 41.2% ± 16.07%) and Iba-1 (macrophages, 48.62% ± 15.07%)." (PMID 37104043, 2023). "One explanation is that blockade of C5aR1 alone is not sufficient to halt the detrimental effects of complement in COVID-19 since C5b-9 is still formed or because C5 can still signal through alternative receptors." (PMID 35945604, 2022). "Notably, the average expression of C5AR1 per cell of the BAL fluid is similar in both patients with COVID-19 and non-COVID-19 pneumonia." (PMID 37104043, 2023). "In addition, the number of C5AR1-expressing neutrophils was higher in the BAL fluid from patients with COVID-19 compared with BAL fluid from patients with non-COVID–19 pneumonia." (PMID 37104043, 2023). "Furthermore, C5aR1 blocking or netosis and thrombin inhibition in neutrophils from COVID-19 subjects was found to diminish platelet-mediated NET-driven thrombogenicity, supporting the pivotal role of complement in net-driven immunothrombosis present in COVID-19 patients." (PMID 38178176, 2024). "Our findings indicating that C5a/C5aR1 signaling in myeloid cells was involved in the lung immunopathology of COVID-19, but not in the infiltration of these cells into the lung, prompted us to hypothesize that this signaling would be involved in the local activation of these cells." (PMID 37104043, 2023).
COVID-19 (continued). "Hence, targeting the C5– C5aR1–GCS glycosphingolipid pathway could protect the SARS-CoV-2-induced development of s severe form of the disease in patients with COVID-19 and GD patients with COVID-19." (PMID 36430817, 2022). "Concentrations of select chemokines (CXCL8, CXCL10, CCL2, CCL3, CCR1) and complement factors (C2, C9, CFD, C4BPA, C5AR1, CR1) were examined at mRNA and protein levels with regard to a COVID-19 course (ICU vs. non-ICU group) and CMV status at different time intervals." (PMID 36232655, 2022). "However, a phase II trial with the receptor C5aR1 antibody avdoralimab (NCT04371367) in mechanically ventilated patients was discontinued for lack of efficacy, so the precise role of C5a in COVID-19 remains unclear." (PMID 35945604, 2022).